ENSG00000249209 (novel protein similar to ATP synthase delta (OSCP) subunit domain)
Gene: Protein-coding gene on chromosome 21 (33,584,687 to 33,931,607, reverse strand). Ensembl gene ENSG00000249209.
Genetic constraint (gnomAD): Loss-of-function variants: 19 observed, 28.92 expected, observed/expected ratio (o/e) 0.66, 90% interval 0.46 to 0.96. Missense variants: 272 observed, 294.72 expected, observed/expected ratio (o/e) 0.92, 90% interval 0.83 to 1.02. Synonymous variants: 111 observed, 107.95 expected, observed/expected ratio (o/e) 1.03, 90% interval 0.88 to 1.2.